TF (transferrin)
Diseases named in the same sentence as TF in open-access papers (continued):
Sharing a sentence is not in itself a finding about the gene and the disease.
infection (continued). "The NNIS score and the evolution of serum IL-6 and various acute-phase proteins (C-reactive protein [CRP], albumin, prealbumin and transferrin) were correlated with postoperative infections and length of hospital stay (LOS)." (PMID 17505683, 2007). "Future prospective, multi-center studies with serial measurements of iron parameters (hepcidin, transferrin saturation), infection biomarkers (procalcitonin), and dialysis adequacy (monthly Kt/V) could further validate our findings." (PMID 41517734, 2026). "After 24 h of infection, a strong increase in the expression of especially SidA, SidD, and SidI was observed, coinciding with the decrease in transferrin protein abundancy; this indicates that a similar system could exist in M. mycetomatis during infection." (PMID 40562743, 2025). "In the lung and systemic circulation, hvKp likely needed aerobactin and yersiniabactin to thrive against host defenses (neutrophils, transferrin/lactoferrin sequestering iron, etc.), and indeed the patient’s initial infection was severe even with those factors." (PMID 41158519, 2025). "These DEGs were subjected to network and functional enrichment analyses to identify gene clusters and functional processes that might explain the protective phenotype of the TF-KO cell line against infection." (PMID 40999544, 2025). "A previous study observed that transferrin levels increased 24 hours post-infection in Ae." (PMID 40632758, 2025). "We detected TF in 6/24 (25.0%) and ocular Ct infection in 4/24 (16.7%) clusters." (PMID 39406720, 2024). "We focused on 22 TF families that were highly expressed at the early stage of infection." (PMID 38143486, 2023). "We conclude that this XRE TF gene cluster, shared by C. crescentus and φCbK, plays an important role in adhesion regulation under phage-free conditions, and influences host-phage dynamics during infection." (PMID 37972151, 2023). "We conclude that an XRE TF gene cluster, shared by C. crescentus and φCbK, plays an important role in adhesion regulation under phage-free conditions, and influences host-phage dynamics during infection." (PMID 37645952, 2023). "We used published Ct infection, TF, and TI prevalence estimates." (PMID 33034349, 2022). "Overall, TF decreased significantly (P<0.005) as did infection (P = 0.01)." (PMID 35830476, 2022). "Transferrin level decreases in infection, inflammation and cachexia." (PMID 35566552, 2022). "In other studies of transgenic mice expressing human transferrin, tbpB mutants were cleared significantly more rapidly than wild-type meningococci, and in human experimental infection models, tbpA/tbpB deletion mutants of the closely related species Neisseria gonorrhoeae did not cause disease." (PMID 36322504, 2022). "The systemic production of NE upon infection is a key feature of the antimicrobial response, and NE stimulates growth by helping to strip Fe from transferrin, which may well be a signal to the pneumococcus to disseminate to the lungs from the upper airway." (PMID 35597283, 2022). "Furthermore, cytokines induce TF expression on circulating monocytes and microparticles during infection which contributes significantly to their procoagulant effect." (PMID 33909679, 2021). "There was a strong correlation between field and photo grading of TF (kappa = 0.69; 95% CI: 0.60–0.78) and between TF and infection, with 21.5% of TF-positive children also testing positive for infection, as compared to only 1.6% of TF-negative children (p = 0.0010)." (PMID 33861754, 2021). "At 6 h post-infection (hpi), the EE system of infected cells is compacted around the cell center and accessible to the incoming endosomal flow, as demonstrated by 45 min internalization of transferrin." (PMID 34440603, 2021). "This is because the model represents the persistence of TF following resolution of infection." (PMID 33596317, 2021).
infection (continued). "Thus, the objective of this study was to evaluate the expression of proteins in the TF of healthy domestic cats before and after inoculation with Toxoplasma gondii, in the acute phase and start of the chronic phase of the infection." (PMID 34906132, 2021). "Previous studies have demonstrated that infection with Cmm induces expression of ERF TF genes." (PMID 34666675, 2021). "The potential for this type of approach has been demonstrated by recent successes in providing protection from infection in the natural porcine host, with vaccine preparations targeting surface receptors involved in acquiring from the host iron-binding protein transferrin." (PMID 32117294, 2020). "Accordingly, patients in our cohort presented with alterations of iron homeostasis parameters being typical for inflammation and infection driven alterations, namely decreased serum iron levels and TF-Sat, decreased serum transferrin levels, and an increase of ferritin concentrations." (PMID 33014378, 2020). "Thus, TF expression is induced both in normal cells (mostly vascular or fibroblastic-type cells and monocytes after injury or infection) and in tumor cells by a variety of inflammatory and growth factors including VEGF, TNFα, IL-1β, IL-6, or IL-8." (PMID 32152404, 2020). "Complement C4 increases in inflammation and infection, and the increased complement C4 in this study may offset and mask the correlation between transferrin and T-lymphocyte count." (PMID 32472529, 2020). "The aims of this study were to demonstrate the utility of non-TF markers by contrasting the relationship between TF and ocular Ct infection in Vanuatu, where infection is suspected to be rare, to that in Kiribati, a neighbouring country where infection is suspected to be more common." (PMID 32017971, 2020). "The data presented here evaluated the effect of a single round of azithromycin MDA on TF, infection with CT, and antibody responses to CT antigens in balozis with an expected TF prevalence between 5 and 9.9%, which until recently (June 2015) was below the threshold for MDA as per WHO guidelines." (PMID 30543311, 2019). "The conclusion that iron availability is important for Mtb during infection is also supported by the observation that high concentrations of transferrin, haptoglobin, and hemopexin are present in the necrotic centers of lung granulomas, the primary sites of infection in human TB patients." (PMID 31534126, 2019). "In the Solomon Islands and Vanuatu, the apparent paucity of TT and ocular Ct infection requires further investigation, particularly of the potential that TF has a causative origin that does not include bacterial infections." (PMID 30440006, 2018). "Also, clathrin-mediated endocytosis signaling pathways, involving molecules such as actin, heat shock proteins, serpin or transferrin, were regulated at all times post-infection with the exception of day 1 pi with E75CV1." (PMID 30208957, 2018). "Here we evaluate how the proportion of TF and PCR positive individuals changes over the course of an intervention period and during re-emergence to assess if, or how, this impacts our probability of detecting infection or disease within a community." (PMID 30307939, 2018). "Effects of diet × infection (p < 0.001) altered liver TF expression." (PMID 30778359, 2018). "During infection, α-antitrypsin and IgA remained higher and transferrin lower in Ghrh−/− animals." (PMID 30333823, 2018). "Thus, in this study, we compare the ability of two mutant TbpBs defective in binding transferrin to protect against infection in the H. parasuis pig infection model." (PMID 29743502, 2018). "There have been suggestions that exogenous administration of transferrin may be an appropriate chelation therapy to reduce infection risks, but this seems counterintuitive as some microorganisms can liberate iron from transferrin." (PMID 28430880, 2017).
infection (continued). "More recently, a high-content imaging study showed that transferrin uptake gradually increased throughout infection of HeLa cells with Coxiella burnetii or Chlamydia trachomatis suggesting that bacterial infection expanded the endosomal system to increase capacity for endocytic material." (PMID 28944216, 2017). "On the other hand, transferrins are considered to participate in innate immune responses of termites through sequestration of iron away from iron-seeking pathogens, and in M. darwiniensis, the transferrin expression was increased after infection with M. anisopliae." (PMID 28410430, 2017). "Furthermore, a high-throughput gene knockout of 104 [Zn(II)2Cys6] TF genes in M. oryzae was performed that suggested their significance in growth, asexual and infection-related development, pathogenesis and response to nine abiotic stresses." (PMID 28659964, 2017). "Interestingly, macrophage infection with the Lp01ΔankX ectopically producing the catalytically inactive AnkXH229A resulted in diminished retention of labeled transferrin compared to macrophages infected with the Lp01ΔankX strain producing active AnkX." (PMID 28944216, 2017). "As a response to infection, an iron sequestering mechanism has developed in mammals that reduces the growth of infecting pathogens by increasing ferritin (intracellular and circulating) and reducing circulating transferrin." (PMID 28873091, 2017). "An important question is why Legionella would manipulate transferrin recycling during infection." (PMID 28944216, 2017). "Moreover, in R. chinensis, the expressions of termicin and transferrin are increased after infection with M. anisopliae." (PMID 28410430, 2017). "Bacterial infection of Ae. aegypti also increases transferrin expression, particularly of AaTf1, suggesting that AaTf1 may play a role in sequestering iron during pathogen infection." (PMID 29387018, 2017). "The inhibitory effect was dependent on Legionella effectors since infection with a translocation-deficient mutant did not disrupt transferrin recycling." (PMID 28944216, 2017). "MiR-184 and miR-4728 were down-regulated in TF independently of Ct infection." (PMID 26842862, 2016). "The prevalence of TF was usually slightly greater than that of infection." (PMID 27783678, 2016). "However, the persistence of TF following resolution of infection at both the individual and population level raises concerns over the suitability of this clinical sign as a marker for C. trachomatis infection." (PMID 27783678, 2016). "A number of conditions such as infection and malignancy can decrease transferrin levels." (PMID 27651883, 2016). "Along with the VSV infection control, we also tested whether siRNA treatment affected the uptake of fluorescently labeled transferrin, which is endocytosed by CME in a dynamin-dependent mechanism." (PMID 26629703, 2015). "Accordingly, both pulmonary and hepatic TF expression is decreased during infection." (PMID 26018580, 2015). "Down-regulation of TF in order to prevent transport of iron from external sources to the site of infection might be another host strategy to lower the level of iron available to the invading bacteria." (PMID 26018580, 2015). "The finding gives further support to the idea that the rounds of MDA were associated with the decline in the association of TF and infection, and not some secular trend that would also affect children aged under one year." (PMID 24722392, 2014). "Odds ratios of infection in children with TF in two specific age groups, with each round of MDA." (PMID 24722392, 2014). "Of the respondents, 46.1 % of surgeons use chlorhexidine baths at home preoperatively for insertions, 42.5 % obtain preoperative laboratories (such as albumin, prealbumin, TWBC, TLC, serum transferrin) to stratify for infection, and 30.8 % obtain MRSA swabs to guide preoperative antibiotic choice." (PMID 24744235, 2014).
infection (continued). "This may suggest that during early infection, the initial strategy of C. albicans is to activate all receptors involved in the detection of ferritin, transferrin, and hemoglobin, to detect possible sources of iron in its surroundings." (PMID 25603810, 2014). "In this study, where the baseline TF prevalence in an area containing 67,000 people was 6.5% in 0–5 year olds, a single round of MDA reduced TF below the elimination threshold, and a test for infection was applied to demonstrate that further rounds of MDA were redundant." (PMID 23785525, 2013). "At 36 months the prevalence of TF was 2.8%, and that of Ct infection was 0.5%." (PMID 23785525, 2013). "In addition, they are responsible for the cleavage of human transferrin which promotes growth and formation of hydroxyl radicals that play an important role in tissue destruction during infection." (PMID 24223061, 2013). "Finally, silencing of transferrin in the fat body tissues of tsetse flies increased the number of trypanosome infections, indicating a role for transferrin in protecting tsetse flies against infection." (PMID 24705082, 2012). "However, no induction was found in Wolbachia-infected flies and wMelPop infection even significantly reduced the expression of transferrin." (PMID 22383881, 2012). "Finally, complementation of ΔcagA with the cagA gene (CagA*) led to restoration of the phenotype of increased transferrin internalization on infection with the bacteria." (PMID 21589900, 2011). "However, various stimuli such as infection and inflammation can induce inflammatory cytokines that increase TF expression and suppress anticoagulant protein expression." (PMID 21489300, 2011). "Approximately a third of the examined children had TF (30.9%, 95% CI: 29.3–32.6), and around half of those were Amplicor positive, demonstrating a strong association between TF and evidence of infection, which was not seen in The Gambia." (PMID 21072224, 2010). "Many conditions, including infection and malignancy, can depress transferrin levels." (PMID 21637603, 2010). "The increase in abundance of transferrin in the plasma in all strains but particularly A/J suggests that iron recycling is not impaired by the infection although the extensive haemolysis caused by the infection makes quantative studies difficult." (PMID 19365556, 2009). "However, it is surprising that Nodavirus infection also resulted in the up-regulation of transferrin and ferritin expression, especially within 24 h of infection." (PMID 19361338, 2009). "In donors, particularly those with terminal illness or ICU admission, undetected infections or systemic inflammatory responses can result in elevated ferritin and low transferrin, which may mimic iron overload and lead to misinterpretation of graft iron status." (PMID 40765572, 2025). "In addition, it is also important to explore whether transferrin can influence pathogen infection in mosquitoes against various pathogens (i.e., bacteria, filarial worms or other diseases)." (PMID 40632758, 2025). "Thus as a survival strategy in the context of infection, bacteria have evolved several mechanisms of iron acquisition, including the removal of haem-iron from host hemoproteins, the acquisition of transferrin and lactoferrin-bound iron, and the uptake of free inorganic iron." (PMID 36246270, 2022). "In this study, the expression of transferrin protein in E. sinensis infected with M. bicuspidata was 3.0 times higher than that in the control group, indicating that it also plays an important role in the innate immunity of E. sinensis against infection by M. bicuspidata." (PMID 33868309, 2021). "Moreover, although A. fumigatus is well-adapted to cause human infection, it is not capable of uptaking iron from sources such as ferritin or transferrin or in the case of hemoglobin only when its concentration is very high, so the fungus has to adapt to starvation during infection." (PMID 34203370, 2021).
infection (continued). "The concurrent analysis and significant correlations between expression of the porcine HP and TF and bacterial afuB and ompP4 peaking short time after bacterial colonization, reveals urgency for both organisms in the attempt of controlling the available iron at the site of infection." (PMID 26018580, 2015). "However, if infection is drastically lowered under antibiotic pressure, then there are fewer opportunities to acquire infection; the result would be a decline in the overall TF prevalence, as was observed here." (PMID 24722392, 2014). "Using in vitro growth and virulence assays and an ex vivo model of infection using human respiratory epithelium 5 μM dopamine or noradrenaline were found to markedly increase P. aeruginosa growth via induction of synthesis of the siderophore pyoverdine and provision of Fe from serum transferrin." (PMID 24381789, 2013). "Notably, although the mRNA levels of transferrin and ferritin, both involved in iron metabolism with spleen and liver as the two main organs, increased in the liver after infection with both pathogens, they increased only in the spleen of V. anguillarum-infected animals." (PMID 19361338, 2009). "While both inhibit the CME-dependent accumulation of transferrin (particularly notable for dynole and IKA), only IKA inhibits EHDV2-Ibaraki infection." (PMID 39981379, 2025). "Upon infection of ‘PI180693’ with either A. euteiches strain, we found TF myb102 (Psat1g209120.1) and abscisic acid and environmental stress-inducible protein encoding gene Psat2g026840.1 to be downregulated." (PMID 38413860, 2024). "We measured transcription of the φCbK genome across an infection cycle and discovered that the phage XRE TF gene, tgrL, is highly expressed at the earliest stages of infection, and we present evidence that TgrL enhances φCbK fitness." (PMID 37972151, 2023). "For example, our study discovered transferrin in A. custos venom, which has been shown to be abundant in the accessory glands extract of the twin-spotted assassin bug P. biguttatus and has been hypothesized to help bugs avoid infection with bacterial pathogens of the captured prey during feeding." (PMID 37237505, 2023). "Increased transferrin uptake and CD71 expression were observed in both NK cell populations from the bone marrow and the spleen following infection, suggesting that responding NK cells have an increased demand for iron." (PMID 34508086, 2021). "To examine the role of clathrin-dependent endocytic pathways in PSV entry and infection of IPEC-J2 cells, we first tested the effect of CPZ on transferrin uptake, which is a model for the CME pathway." (PMID 30909932, 2019). "Four out of six C2H2 TF genes were differentially expressed; one (TFSSR014) was up-regulated in the early stages of pathogen infection (0 h, 1 d, 2 d), and the other two (TFSSR034, TFSSR017) were up-regulated in the later stages of infection (2 d, 5 d, 7 d)." (PMID 29443955, 2018). "At the population level, the prevalence of infection declines more rapidly than the prevalence of TF following MDA with some studies showing that TF persists at levels >10% within the population for months or years after infection has subsided." (PMID 25714363, 2015). "While increased expression of TfR1 leads to an increase in the labile iron pool when exposed to iron-loaded transferrin, the overall labile iron pool (LIP) of the host cell can be affected in many different ways during infection." (PMID 20184753, 2010). "Furthermore, ingested iron is absorbed and chelated with lactoferrin or other transferrin proteins, potentially blocking viral entry into the host cell by inhibiting cellular receptors or directly binding to viral particles, which may play a role in blocking early stages of infection." (PMID 40008312, 2025). "Therefore, the decrease in TF and TIBC during infection (negatively correlated with WBC and NEUT%) is essentially an active defense by the host to reduce the availability of “bacterial iron carriers”." (PMID 41280746, 2025).